BLTP3B (bridge-like lipid transfer protein family member 3B)
Description:
Tube-forming lipid transport protein which mediates the transfer of lipids between membranes at organelle contact sites. Required for retrograde traffic of vesicle clusters in the early endocytic pathway to the Golgi complex.
Synonyms: KIAA0701; SHIP164; UHRF1BP1L; SHIP164A
Tractability: PROTAC: ubiquitination databases record sites on it.
Gene: Protein-coding gene on chromosome 12 (100,028,455 to 100,142,886, reverse strand). Ensembl gene ENSG00000111647.
Subcellular location: Cytoplasm, cytosol; Early endosome
Subcellular location (Human Protein Atlas): Nucleoplasm; Cytosol; Vesicles
Pathways (Reactome):
Signal Transduction: RND2 GTPase cycle
Gene Ontology:
Molecular function: GARP complex binding; lipid transfer activity; protein binding; protein homodimerization activity
Biological process: early endosome to Golgi transport; intermembrane lipid transfer
Cellular component: cytosol; early endosome
Genetic constraint (gnomAD): Loss-of-function variants: 61 observed, 130.65 expected, observed/expected ratio (o/e) 0.47, 90% interval 0.38 to 0.58. The upper end of that interval is the gene's LOEUF score, 0.58, which puts it in group 2 of 6, group 1 being the genes least tolerant of losing a copy. Missense variants: 1,498 observed, 1,692.4 expected, observed/expected ratio (o/e) 0.89, 90% interval 0.85 to 0.92. Synonymous variants: 554 observed, 572.49 expected, observed/expected ratio (o/e) 0.97, 90% interval 0.9 to 1.04.
Homologues: Orthologues: chimpanzee BLTP3B (99% identical), macaque BLTP3B (99% identical), pig BLTP3B (92% identical), dog BLTP3B (91% identical), guinea pig BLTP3B (88% identical), mouse Bltp3b (85% identical), rat Bltp3b (82% identical), tropical clawed frog bltp3b (58% identical), zebrafish bltp3b (50% identical), Drosophila melanogaster CG34126 (27% identical), Caenorhabditis elegans C44H4.4 (16% identical). Paralogues in human: BLTP3A (41% identical).
Diseases named in the same sentence as BLTP3B in open-access papers:
BLTP3B is named in the same sentence as 3 diseases in open-access papers, as found by Europe PMC text mining. Sharing a sentence is not in itself a finding about the gene and the disease.
BLTP3B shares sentences with these, for which no sentence is quoted: fibrosis (1 paper); myopia (1); Parkinson disease (1).